MALAT1 (metastasis associated lung adenocarcinoma transcript 1)
Diseases named in the same sentence as MALAT1 in open-access papers (continued):
Sharing a sentence is not in itself a finding about the gene and the disease.
cancer (continued). "MALAT1 has been found to manipulate proliferation, migration and apoptosis in many different human cancers such as pancreatic cancer, lung cancer and ovarian cancer." (PMID 32209098, 2020). "It is one of the most highly expressed lncRNAs in normal tissues and MALAT1 levels correlate with poor clinical outcomes in cancer." (PMID 32292999, 2020). "Here, we discuss the current state-of-knowledge in regard to MALAT1 function and its putative role in several disease states, including cancer." (PMID 32503170, 2020). "We also detected a strong reduction of XIST, NEAT1 and MALAT1, three conserved nuclear lncRNAs with well-known links to a broad range of cancer types." (PMID 32727085, 2020). "A previous meta-analysis has shown that the up-regulation of MALAT-1 is significantly correlated with the prognosis and metastasis of cancers." (PMID 32700729, 2020). "Overexpression of MALAT1 was found in COAD tumor samples and further clinical assess indicated that high MALAT1 expression was -significantly associated with advanced cancer stage." (PMID 32209115, 2020). "LncRNA MALAT1 located on the chromosome 11q13, is also suggested to be involved in elevating the malignancy of cancer cells." (PMID 32664703, 2020). "Malat1 has been termed an oncogene, which is upregulated in many cancers and promotes cancer initiation and progression." (PMID 31695627, 2019). "Since the discovery of MALAT1, many other lncRNAs have been shown to play a direct role in nearly every major cancer type." (PMID 30894871, 2019). "While it is unclear how this U4056C mutation in MALAT1 would contribute to the progression of cancer, elevated levels of miR-23 have been shown to increase epithelial-mesenchymal transition (EMT) in cancer cells." (PMID 31717552, 2019). "MALAT1 has been found to control proliferation, migration, and apoptosis in many different human cancers, and its overexpression has also been correlated with drug resistance." (PMID 30654440, 2019). "Several recent studies have reported roles for lncRNAs in cancer, including MALAT1 and GAS, strongly indicating that lncRNAs not only control gene regulatory pathways in normal cells and tissue, but also during tumor development." (PMID 31890219, 2019). "This fits well with the known role of MALAT1 as global regulator of cancer genes and orchestrator of a global transcriptional response." (PMID 31142264, 2019). "Considering its implications in cell proliferation, and generally in cancer progression, MALAT1 is a potential therapeutic target for cancer treatment." (PMID 30654440, 2019). "Although emerging reports have described the function of MALAT-1 in cancers, knowledge gaps remain regrading the mechanism for cancer pathogenesis." (PMID 31350456, 2019). "LncRNAs such as HOTAIR, MALAT1, GAS5, PC3, and H19 are aberrantly regulated in various malignant tumors and associated with carcinogenesis, metastasis, and prognosis." (PMID 31141943, 2019). "Although the role of MALAT1 has been explored in diverse cancers, its biological function in the DTX resistance of LUAD still needs to be elucidated." (PMID 30771618, 2019). "The lncRNA MALAT1 (metastasis-associated lung adenocarcinoma transcript 1), found in EVs derived from NSCLC, has been implicated in cancer growth and migration." (PMID 31752198, 2019). "Subsequently, overexpression of MALAT1 was shown to exhibit marked effects on tumor cell proliferation, migration, invasion, and apoptosis in numerous types of cancer." (PMID 31500187, 2019). "Recent studies have suggested that the lncRNA metastasis-associated lung adenocarcinoma transcript 1 (MALAT1), located on chromosome 11q13, which is involved in the process of EMT in the cancer." (PMID 31143769, 2019). "To date, there are more than 800 publications related to MALAT1 (the PubMed search word “MALAT1” generated 809 results as of 13 February, 2019) and many of them reported a role of MALAT1 in cancer, making MALAT1 one of the most studied lncRNAs." (PMID 30781877, 2019).
cancer (continued). "MALAT1 expression is upregulated in various cancers and thus has been proposed as a prognostic biomarker of metastasis." (PMID 30788509, 2019). "For instance, by modulating Wnt signaling, MALAT1 has been shown to regulate cancer cell EMT, migration, invasion, and metastasis." (PMID 30781877, 2019). "It has been shown that autophagy is associated with poor outcome and is effective as a prognostic marker in CRC.Recently, an increasing number of studies have revealed that Malat1 promotes tumorigenesis by stimulating autophagy in many cancers." (PMID 31372165, 2019). "Collectively, multiple datasets converging on a cohesive structural model provide a starting point for developing new models of how the structure of MALAT1 relates to its biological functions, especially in cancer." (PMID 31717552, 2019). "Metastasis-associated lung adenocarcinoma transcript 1 (MALAT1) is a lncRNA linked with the breast, lung, and other cancer development." (PMID 31777593, 2019). "Metastasis-associated lung adenocarcinoma transcript 1 (MALAT1), also known as nuclear-enriched abundant transcript 2 (NEAT2), is a highly expressed nuclear lncRNA, frequently upregulated in cancer, that contains several m6A modifications." (PMID 31316981, 2019). "MALAT-1, a lncRNA which is highly expressed in many types of cancer, can also suffer m1A modification in A8398 position." (PMID 30654440, 2019). "In recent years, a numbers of lncRNAs [LncRNA uc.372, SNHG16, SNHG1, or MALAT1] were observed to negatively regulate miR-16 family member expression and played a role in pathogenesis of cancers." (PMID 31316397, 2019). "Actually, messenger (m)RNA expression levels of MALAT1 were significantly lower in PTC patients or cancer-free subjects who harbored the AG + GG genotype than those with the AA genotype." (PMID 31500187, 2019). "MALAT1, which also functions as an oncogene transcript involved in diverse cancer types, was proposed to modulate the phosphorylation status of SR proteins in the nucleus, including the MALAT1-interacting SRSF1." (PMID 31698782, 2019). "By regulating gene expression and coordinating splicing, MALAT1 is practically involved in cell cycle and proliferation dysregulation, as well as cell migration and metastasis in several types of cancer." (PMID 30654440, 2019). "Because of the important roles of MALAT1 in many diseases, especially cancer, MALAT1 is receiving more and more attention." (PMID 31168355, 2019). "Increasing reports have demonstrated that Malat1 is highly expressed in different types of cancer patients and has a strong relationship with the prognosis of cancer patients." (PMID 31372165, 2019). "lncRNA Malat1, which was discovered in cancer cells, can promote the proliferation of cancer cells and tumor progression." (PMID 31546877, 2019). "One of the most studied lncRNAs, MALAT1 is involved in several dysregulations found in cancer and is responsible for coordination of alternative splicing." (PMID 30654440, 2019). "Previous studies revealed that MALAT1 functions as a molecular sponge to inhibit miRNA expression, and plays a significant role in cancer pathogenesis." (PMID 31101802, 2019). "A recent pan‐cancer study predicts that NEAT1 is the lncRNA which has the most cancer gene targets closely followed by the lncRNA MALAT1, LINC00969, and OIP5‐AS1." (PMID 30430751, 2019). "The findings in this paper will further enhance the understanding of the mechanism of action of MALAT1 involved in malignant tumor progression and provide new targets for molecular diagnostics and treatment of HCC." (PMID 31466138, 2019). "The LncACT-Function tool performs functional analysis of MALAT1 based on GO terms, pathways and cancer hallmarks." (PMID 30476305, 2019). "Metastasis-associated lung adenocarcinoma transcript 1 (MALAT1) is one of the long non-coding RNAs that plays an important role in invasion, cell proliferation, and metastasis of various cancers." (PMID 32099603, 2019).
cancer (continued). "In cancer cells, MALAT1 can further disrupt the formation of a splicing modulator complex through hijacking the SFPQ factor (proline- and glutamine-rich SF; or PSF for PTB-associated SF), thereby inhibiting its interaction with the tumour growth factor PTBP2." (PMID 31698782, 2019). "Upregulation of MALAT1 was observed in many kinds of cancers, like oral, bladder, and colorectal carcinomas, as well as osteosarcoma." (PMID 31208095, 2019). "lncRNAs play an important role in cancer mainly via their associations with RNA-binding g proteins, which include HOTTIP, MaLAT1, H19, and HOTAIR." (PMID 31827401, 2019). "Existing research suggests that Malat1 is involved in the pathogenesis of various human diseases, especially cancer." (PMID 31695627, 2019). "By characterizing this sense/anti-sense pair we uncovered the complexity of MALAT1 locus regulation, describing new potential candidates for cancer targeting." (PMID 31382922, 2019). "There have been many studies on the abnormal expression of MALAT1 in a variety of diseases; however, studies on MALAT1 promoter methylation and its role in cancer are scarce." (PMID 32099603, 2019). "Overall, differential MALAT1 regulation and processing is therefore supporting its distinct role either promoting cancer growth or co-existing in healthy tissues." (PMID 31382922, 2019). "Much research has focused on the functions of lncRNAs because of their simultaneous participation in multiple steps of cancer progression or simultaneous involvement in multiple types of cancer, as is the case for MALAT1." (PMID 31248165, 2019). "MALAT1 was significantly overexpressed in cancer subsets (Stage III and Stage IV) with respect to other subsets (Stage I and Stage II)." (PMID 31168355, 2019). "Malat1 has been extensively studied in pan-cancer and is reportedly an anti-oncogene, but its autophagy function in macrophage has rarely been reported." (PMID 31425535, 2019). "Due to its multiple roles in different types of cancer, MALAT1 has recently received much attention as a therapeutic target for clinical applications." (PMID 32099603, 2019). "After discovery of MALAT1, its overexpression in many cancers has been a study of focus for many years." (PMID 31866580, 2019). "An emerging theme from our study is that the structure of MALAT1, which can be perturbed by RNA modifications, mutations in cancer, and SNPs, plays a critical role in mediating MALAT1–miRNA interactions in cancer." (PMID 31717552, 2019). "In contrast to the gene deletion model, our group found that Malat1 wild-type, Malat1-inactivated, and Malat1-overexpressing PyMT tumors showed similar degrees of cystic areas and high-grade carcinoma areas." (PMID 30781877, 2019). "MALAT1 is the first discovered and most widely investigated lncRNA, in terms of both functional activity and therapeutic potential for cancer treatment." (PMID 29739426, 2018). "Some studies suggested that MALAT1 can promote the progression in several kinds of cancers through different mechanisms, including activating downstream PI3K/AKT, regulating transcription and alternative splicing, and stimulating EMT of tumors." (PMID 29416769, 2018). "The pro-tumorigenic activity of SRSF1 has been recently established, and a whole genome analysis has identified multiple mutations in SRSF1-binding sites of MALAT1, pointing to a role for SRSF1/MALAT1 interaction in cancer pathogenesis." (PMID 29739426, 2018). "The contribution of each function to the tumorigenic activity of MALAT1 within specific tumor types will be also discussed in the paragraph “MALAT1 role in cancer”." (PMID 29739426, 2018). "To evaluate the cuRnet performance in making highly confident ncRNA function predictions, we analysed a case study with the well-known lncRNA involved in cancer called MALAT1." (PMID 30367572, 2018). "MALAT1 showed a very prominent staining in these three cancer tissues, mostly in epithelial cell populations." (PMID 30189670, 2018).
cancer (continued). "Malat1 is a long noncoding RNA with a wide array of functions, including roles in regulating cancer cell migration and metastasis." (PMID 29912916, 2018). "Most well documented in cancer, one prominent intergenic lncRNA known as MALAT1 is notorious for its role in impacting epigenetic mechanisms." (PMID 29695738, 2018). "We ultimately chose to focus on Malat1 in subsequent experiments, primarily because of its important role in cancer, the precise nature of which remains a controversial subject." (PMID 29912916, 2018). "In DLD-1 and HT-29, the number of cancer cells in the G1 phase increased in the si-MALAT1 group while decreased in miR-145 inhibitor group in contrast to the NC group." (PMID 30285605, 2018). "To evaluate the importance of miR663a in the oncogenic effects of MALAT1 on cancer cells, we performed IncuCyte long-term dynamic proliferation/migration and Transwell invasion analysis." (PMID 30154407, 2018). "In most studies, high MALAT1 expression correlates with metastasis, invasion and chemoresistance of cancers." (PMID 29484127, 2018). "Mechanistically, Malat1 appears to regulate gene expression, which results in the effects on cell migration and metastasis in cancer." (PMID 29912916, 2018). "Using these cells, we assess how the link between Nischarin and Malat1 affects cancer cell function, finding that Malat1 confers an inhibitory effect on cell growth and migration which is lost following Malat1 KO, but in a Nisch-dependent context." (PMID 29912916, 2018). "The aberrant regulation of MALAT1 has been indicated to be involved in various carcinogenic pathways contributing to the tumourigenesis and progression of cancers." (PMID 30093838, 2018). "Since its initial discovery, MALAT-1 has been shown to be overexpressed and linked to the promotion of EMT in many cancers." (PMID 29701689, 2018). "The lncRNA MALAT1 has multiple biological functions, including influencing RNA processing, miRNA sponging, and cancer development." (PMID 30154407, 2018). "The roles of a small number of lncRNAs such as HOTAIR, H19, and MALAT1 have been depicted in cancers, but little is known about LINC00470." (PMID 29866190, 2018). "The negative prognosis associated with overexpression of MALAT-1 in tumors correlates with the functions of MALAT-1 in cancer cells." (PMID 29389953, 2018). "MALAT1 is a highly conserved LncRNA that is highly expressed in several types of cancer, including BC." (PMID 30459529, 2018). "Invasive breast tissues have been shown to have higher MALAT1 expression, but for the first time this study gives visual evidence in multiple cancer types." (PMID 30189670, 2018). "Overall, increased MALAT1 expression is deleterious to cancer metastasis due to cell migration, but its application to wounds via exosomes derived from stem cells appears therapeutic." (PMID 30263873, 2018). "Herein, we conducted a systematic review and meta-analysis to elucidate the relationship of MALAT1 with prognosis or clinical features and generalized its tumorigenicity among different cancers." (PMID 30093838, 2018). "Several lncRNAs reportedly having crucial roles in cancer, including HOTAIR, MALAT1 and H19, have been reported to be linked to survival." (PMID 30038703, 2018). "The observation that this type of cancer exhibits low levels of Malat1 in human samples as well signals the potential usefulness of using this cell line to study Malat1 in our Nisch-dependent context." (PMID 29912916, 2018). "Though MALAT1 has been studied in different cancers as a poor prognostic, aggressive, and metastatic marker, most of the published data on MALAT1 lack visual representation of MALAT1 detection." (PMID 30189670, 2018). "As a novel and representative lncRNAs, MALAT1 was found to be highly expressed in several kinds of cancer." (PMID 29416769, 2018).
cancer (continued). "It has been discovered in research on MDA-MB-231 that KDM5B regulates MDA-MB-231 as a carcinogenic gene and the downregulation of KDM5B leads to lower expression of MALAT1 while decreasing invasion of cancer cells." (PMID 30459529, 2018). "Some lncRNAs are expressed in a cell type-specific manner during differentiation and in certain cancers, whereas several lncRNAs such as MALAT1 are widely overexpressed in various cancers." (PMID 30374364, 2018). "A recent report showed that MALAT-1 is an Sp1-regulated gene and we therefore determined if ROS-inducing anticancer agents that downregulate Sp1, Sp3 and Sp4 in pancreatic and other cancer cell lines also decrease MALAT-1 expression." (PMID 29389953, 2018). "MALAT1 is among the first lncRNAs identified as promoting metastasis and proliferation of different cancers through alternative splicing and gene expression." (PMID 29449542, 2018). "A network analysis of ncRNAs in cancer drug resistance-associated lncRNAs–miRNAs, TAM resistance (including lncRNAs MALAT1 and CCAT2; miR-221, miR-222, miR-26a, miR29a, miR-29b), and Trastuzumab resistance (lncRNA GAS5, miR-16, and miR-155) has been described." (PMID 30545127, 2018). "Functionally, MALAT1 promotes the development of cancer through a variety of mechanisms that regulate cancer cell radiosensitivity and chemical sensitivity, such as miRNA sponging, enhanced EMT and stimulated autophagy." (PMID 29435112, 2018). "Later, discovery of MALAT1 dysregulation was expanded into various cancers to become the key regulator of metastasis and cancer development." (PMID 30127741, 2018). "Prominent lncRNA MALAT1 staining encouraged us to utilize this assay to analyze MALAT1 as a cancer progression and invasiveness marker." (PMID 30189670, 2018). "The same authors showed that MALAT1 is regulated by epigenetic mechanisms, since methylation of CpG islands at MALAT1 promoter decreased in cancer as compared to normal tissues." (PMID 29739426, 2018). "It has already been revealed that some lncRNAs, such as HOTAIR, H19 and MALAT1, are potential biomarkers in cancer diagnosis and prognosis." (PMID 29549263, 2018). "Previous studies suggest that the interaction between MALAT1 and serine/arginine splicing factors act a pivotal part in cancer progression, synapse formation, and growth signal responsive genes expression." (PMID 30018955, 2018). "Depletion of Malat1, on the other hand, inhibits cell motility in vitro and significantly limits metastasis formation in mouse cancer models." (PMID 29891768, 2018). "Increasing lncRNAs have been reported to regulate cancer pathways and participate in cancer development, such as the well-characterized MALAT1, H19, HOTAIR and MEG3." (PMID 29849506, 2018). "MALAT1 expression and functional role in the onset and/or progression of different cancer types, along with the therapeutic potential of MALAT1 targeting strategies, will be below discussed." (PMID 29739426, 2018). "Altogether, literature data indicate aberrant expression and dysregulated activity of MALAT1 in human malignancies and envision MALAT1 targeting as a novel treatment strategy against cancer." (PMID 29739426, 2018). "Consistent with results of our experiments, previous studies also suggested that higher expression of MALAT1 significantly correlated with metastasis in patients with cancers through the transcriptional and post-transcriptional modulation." (PMID 30285605, 2018). "The current meta-analysis summarized the research advances of MALAT1 functions and analyzed its prognostic value among multiple types of cancers." (PMID 30093838, 2018). "It has also been postulated that, aberrant expression of MALAT1 modulate autophagy in various cancers including glioma, GC, HCC, and RTB by controlling micro RNAs miR-216b, miR-101, miR-124, and miR-23b-3p." (PMID 30693021, 2018).